MUC13 (mucin 13, cell surface associated)
Description:
Epithelial and hemopoietic transmembrane mucin that may play a role in cell signaling.
Synonyms: MUC-13; DRCC1
Tractability: Antibody: UniProt places it where antibodies can reach, with high confidence; its Gene Ontology location is reachable by antibodies, with high confidence; UniProt predicts a signal peptide or a membrane-spanning region. PROTAC: ubiquitination databases record sites on it; its protein half-life has been measured.
Gene: Protein-coding gene on chromosome 3 (124,905,440 to 124,953,819, reverse strand). Ensembl gene ENSG00000173702.
Subcellular location: Cell membrane; Apical cell membrane; Secreted
Pathways (Reactome):
Disease: Defective C1GALT1C1 causes TNPS; Defective GALNT12 causes CRCS1; Defective GALNT3 causes HFTC
Signal Transduction: RND1 GTPase cycle; RND2 GTPase cycle; RND3 GTPase cycle
Metabolism of proteins: O-linked glycosylation of mucins; Termination of O-glycan biosynthesis
Immune System: Dectin-2 family
Gene Ontology:
Molecular function: protein homodimerization activity
Biological process: maintenance of gastrointestinal epithelium
Cellular component: apical plasma membrane; cytosol; extracellular region; Golgi lumen; plasma membrane
Genetic constraint (gnomAD): Loss-of-function variants: 29 observed, 47.46 expected, observed/expected ratio (o/e) 0.61, 90% interval 0.45 to 0.83. The upper end of that interval is the gene's LOEUF score, 0.83, which puts it in group 3 of 6, group 1 being the genes least tolerant of losing a copy. Missense variants: 557 observed, 634.04 expected, observed/expected ratio (o/e) 0.88, 90% interval 0.82 to 0.94. Synonymous variants: 193 observed, 229.71 expected, observed/expected ratio (o/e) 0.84, 90% interval 0.75 to 0.95.
Homologues: Orthologues: chimpanzee MUC13 (95% identical), macaque MUC13 (76% identical), pig MUC13 (47% identical), mouse Muc13 (42% identical), rat Muc13 (41% identical), dog MUC13 (40% identical). Paralogues in human: MUC17 (19% identical), MUC3A (17% identical).
Diseases named in the same sentence as MUC13 in open-access papers:
MUC13 is named in the same sentence as 79 diseases in open-access papers, as found by Europe PMC text mining. Sharing a sentence is not in itself a finding about the gene and the disease. The quoted sentences say what the papers report.
pancreatic cancer (17 papers, 2008 to 2026). "MUC13, a newly discovered transmembrane mucin that was found to be overexpressed in pancreatic cancer, is associated with dysregulation of PAK1." (PMID 35566098, 2022). "We demonstrate the metabolic alterations induced by MUC13 in pancreatic cancer cells and the underlying molecular mechanisms that drive the associated tumorigenic characteristics." (PMID 29467405, 2018). "Taken together, this study provides the first comprehensive elucidation of the MUC13-associated molecular interactome, which may contribute to pancreatic cancer progression and metastasis." (PMID 42028237, 2026). "miR-145 functions as a tumor-suppressor in pancreatic cancer and inhibits the expression of the mucin 13 (MUC13) gene." (PMID 35883598, 2022). "For example, in 2014, miR-145 was suggested to act as a tumor suppressor and regulator of MUC13, which is aberrantly overexpressed in pancreatic cancer." (PMID 34440625, 2021). "Cuc D administration showed a significant reduction (p < 0.05) in the expression of PCNA and MUC13 protein levels in excised xenograft tumor tissues, further indicating that Cuc D has the potential to inhibit xenograft-derived human pancreatic cancer cells." (PMID 31906106, 2019). "MUC13 functionally interacts and stabilizes Glut-1 to instigate downstream events responsible for higher glucose uptake in pancreatic cancer cells." (PMID 29467405, 2018). "In the present study, we report a novel role of MUC13 in metabolic reprogramming of pancreatic cancer." (PMID 29467405, 2018). "MUC13 has been recently reported to functionally interact with HER2 and this interaction mediates MUC13-induced pancreatic cancer progression." (PMID 29467405, 2018). "Analysis of MUC13 and Glut-1 expression in both the sets revealed a positive correlation between the expressions of these genes in human pancreatic cancer tissues." (PMID 29467405, 2018). "To understand clinical correlation of MUC13-Glut-1 molecular interaction, we examined human pancreatic cancer tissues for MUC13 and Glut-1 expression using qPCR technique." (PMID 29467405, 2018). "Herein, we have identified MUC13 as a novel molecular target responsible for increased glucose metabolism in pancreatic cancer cells." (PMID 29467405, 2018). "Our study provides the first evidence for the critical involvement of MUC13 in metabolic reprogramming of pancreatic cancer cells by activating the NF-κB survival pathway and molecular interaction with Glut-1 receptor." (PMID 29467405, 2018). "A positive correlation between the expression of MUC13 and Glut-1 in human pancreatic cancer tissues suggest clinical correlation of our proposed novel mechanism related to aberrant glucose metabolism in pancreatic tumors." (PMID 29467405, 2018). "MUC13 protein, is a transmembrane mucin, which is aberrantly expressed in pancreatic cancer and enhances pancreatic tumor progression through various mechanisms; one such mechanism is being mediated through its interaction with HER2, a member of EGFR family." (PMID 29467405, 2018). "Altered MUC13 expression by overexpression and knockdown techniques effectively modulated glucose uptake, lactate secretion, and metastatic phenotypes in pancreatic cancer cells." (PMID 29467405, 2018). "Briefly, our study delineate the role of MUC13 in aberrant glucose metabolism in pancreatic cancer and suggest it as a novel molecular target for therapeutic intervention of this frightening disease." (PMID 29467405, 2018). "Recently, we have shown that MUC13, which is highly expressed in pancreatic tumors, promotes tumor progression via modulation of HER2 receptor tyrosine kinase activity." (PMID 29467405, 2018). "Herein, we investigate a novel, MUC13-mediated molecular mechanism responsible for higher glucose metabolism in pancreatic tumors." (PMID 29467405, 2018).
pancreatic cancer (continued). "Our observations suggest that the reliance of pancreatic tumor growth and metastasis on MUC13-Glut-1 mediated glucose metabolism can be exploited for the development of novel targeted therapeutic strategies for pancreatic cancer." (PMID 29467405, 2018). "Our studies indicate that the MUC13-induced metabolic alterations require NF-κB activation that precedes the triggering of events in controlling glucose metabolism in pancreatic cancer cells." (PMID 29467405, 2018). "Another study demonstrated that miR-145 can suppress tumor growth of pancreatic cancer through its inhibitory effects on MUC13." (PMID 27911274, 2017). "High expression of MUC13 also predicts an inferior outcome of patients with colorectal cancer, esophageal squamous cell carcinoma and pancreatic cancer." (PMID 27911274, 2017). "For example, miR-494 negatively regulates the expression of FOXM1, and miR-145 inhibits the expression of MUC13, to inhibit the proliferation, invasion, and metastasis of pancreatic cancer." (PMID 27494897, 2016). "Herein, we report a novel microRNA (miR-145)-mediated mechanism regulating aberrant MUC13 expression in pancreatic cancer." (PMID 25277192, 2014). "We report that miR-145 expression inversely correlates with MUC13 expression in pancreatic cancer cells and human tumor tissues." (PMID 25277192, 2014). "The present work suggests that miR-145 is a tumor suppressor in pancreatic cancer and a novel regulator of MUC13 expression." (PMID 25277192, 2014). "Our investigations revealed that miR-145 is inversely correlated to MUC13 expression in PanCa cell lines and pancreatic tumor tissues." (PMID 25277192, 2014). "Mucin-13 (MUC13) has emerged as a critical molecular player involved in tumorigenesis, cancer progression, metastasis, and evasion of immune surveillance, including in pancreatic cancer." (PMID 42028237, 2026). "In digestive system cancer research, MUC13 was observed to be highly expressed in pancreatic cancer, impacting HER2 receptor tyrosine kinase activity, which initiated NF-κB p65 activation and nuclear translocation, along with IκB phosphorylation, thereby enhancing tumor progression." (PMID 39309442, 2024). "Consistent with RUNX1 expression patterns, significant overexpression of MUC13 was observed in various gastrointestinal cancers, such as cholangiocarcinoma, colon cancer, esophageal cancer, hepatocellular carcinoma, pancreatic cancer, rectal cancer, and gastric cancer." (PMID 39309442, 2024). "The expression of MUC13 also leads to the activation of NF-κB p65 nuclear translocation and phosphorylation of IκB, which in turn upregulates the expression of important proteins involved in glucose metabolism to promote the invasion of pancreatic cancer." (PMID 37395858, 2023). "MUC13 supports multiple signaling pathways in the pancreatic tumor microenvironment." (PMID 35883598, 2022). "Therefore, our results demonstrate that MUC13 enhances glucose metabolism of pancreatic cancer cells." (PMID 29467405, 2018). "In summary, this study revealed a novel role of MUC13 in rewiring of a distinct glucose metabolic network that drives favorable tumor microenvironment and oncogenic signaling pathways in pancreatic cancer cells for the adoption of their enhanced tumorigenic and metastatic behavior." (PMID 29467405, 2018). "Previous reports demonstrate that MUC13 enhances invasion and migration in pancreatic cancer cells." (PMID 29467405, 2018). "In addition, increased expression of oncogenic KRAS was observed in MUC13-expressing cells that is known to maintain pancreatic tumors through regulation of anabolic glucose metabolism." (PMID 29467405, 2018). "Recently, a number of studies found that MUC13 was overexpressed in many malignancies including colon cancer, gastric cancer, ovarian cancer, esophageal squamous cell carcinoma, and pancreatic cancer." (PMID 27911274, 2017). "MUC13, a transmembrane mucin is highly involved in pancreatic cancer progression." (PMID 25277192, 2014).
pancreatic cancer (continued). "However, strong expression of Muc13 in 50% of samples as well as b-myc in pancreatic cancer cells was unexpected and needs further characterization." (PMID 18218118, 2008). "Aberrant expression of MUC13 has been observed in various solid tumors, including hepatocellular carcinoma 25, gastric cancer 26, pancreatic cancer 27, renal cancer 28, ovarian cancer 29, and lung cancer 30, suggesting that MUC13 may have a cancer-promoting effect." (PMID 39309442, 2024). "Regarding mucins other than MUC1, pancreatic cancer cells become resistant to gemcitabine in parallel with MUC4 expression, and MUC13 overexpression in renal cell carcinoma was reported to play a central role in tumor progression and drug resistance." (PMID 35410995, 2022). "MUC13 also has effects on glucose metabolism in PDAC, which is important for survival of the PDAC cancer in the hostile pancreatic tumor microenvironment." (PMID 35883598, 2022). "Thus, inhibition of MUC13 via conventional pharmacological agents and/or non-conventional small interfering RNA/microRNA-mediated technologies can selectively suppress pancreatic tumor growth and metastasis via inhibition of glycolytic influx in PanCa cells." (PMID 29467405, 2018).
ovarian carcinoma (12 papers, 2009 to 2025). A malignant neoplasm originating from the surface ovarian epithelium. "In ovarian cancer, reduced methylation at CpG sites in MUC13's promoter resulted in overexpression, significantly enhancing the migratory and invasive abilities of cancer cells." (PMID 39309442, 2024). "MUC13, a relatively high-molecular-weight glycoprotein secreted by mucosal tissue, has been shown to promote the development of various tumors, including ovarian cancer and colorectal cancer, by regulating numerous signaling pathways." (PMID 36700475, 2022). "MUC13 has previously been found to have aberrant expression in ovarian cancer compared to normal ovarian tissue, especially in MC samples both compared to other histological OC types as well as adjacent normal tissues." (PMID 36818673, 2022). "Nevertheless, MUC13 has been widely reported to regulate various cancers, including ovarian cancer, colon cancer, colorectal cancer, and gastric cancer." (PMID 36700475, 2022). "Analysis of one mRNA microarray indicated that 444 genes were upregulated and 529 genes were downregulated; the expression of mucin 13 (MUC13) mRNA was significantly elevated in metastatic implants from ovarian cancer xenografts versus ovarian cancer cells." (PMID 34631583, 2021). "Extracellular luminal staining data of a previous study implied that it was possible for MUC13 to release into the secretions and/or blood after shedding from the ovarian cancer cells." (PMID 27911274, 2017). "MUC13 is another potential mucin which is highly expressed on the surface of ovarian cancer cells, indicating its potential as a target for RID and RIT." (PMID 20034397, 2009). "In this study, MUC13 expression was undetectable in normal and benign ovarian samples while 66% of epithelial ovarian cancer samples showed a significantly higher MUC13 expression." (PMID 20034397, 2009). "Recently, our laboratory has identified aberrant expression of a novel membrane anchored mucin, MUC13, in ovarian cancer." (PMID 20034397, 2009). "Moreover, MUC13 expression was significantly (p < 0.05) higher in mucinous and Brenners type of samples compared to other histological types of ovarian cancer samples and adjacent normal ovary samples." (PMID 20034397, 2009). "One of these studies illustrated that exogenous MUC13 expression correlated with remarkable reduction in cell-cell adhesion and significantly (p < 0.05) increases cell motility, proliferation, and tumorigenesis in a xenograft mouse model system with ovarian cancer." (PMID 27911274, 2017). "Another interesting gene identified to be under positive selection is mucin 13 (MUC13), a transmembrane glycoprotein expressed in gastric, colorectal and ovarian cancers." (PMID 24194868, 2013). "Other than MUC16, ovarian cancer cells also overexpress MUC1, MUC9, and MUC13." (PMID 32785160, 2020). "Moreover, knockdown of the glycosyltransferase responsible for synthesis of MUC1 and MUC13, N-acetylgalactosaminyltransferase 3 (GALNT3) and GALNT14, respectively, reduces migration of ovarian cancer cells." (PMID 32785160, 2020). "However, co-expression of GalNAcT14 and transmembrane mucin 13 (Muc13) in ovarian cancer tissues, but not in normal tissues, suggested a contribution of GalNAcT14 to ovarian carcinogenesis through aberrant glycosylation of Muc13." (PMID 27322213, 2016). "In addition to MUC16, MUC13 may be useful in detecting some subtypes of nonserous ovarian carcinomas and early-stage ovarian carcinomas (stages I and II)." (PMID 37664708, 2023).
colitis (10 papers, 2010 to 2025). Inflammation of the colon. "Conversely, Muc13−/− mice are more susceptible to acute DSS-induced colitis by promoting epithelial cell apoptosis but deficiency of Muc13 expression during chronic colitis reduced the risk for tumor formation in azoxymethane (AOM)/DSS-treated mice." (PMID 37174625, 2023). "On the contrary, our data suggested an enhanced recovery upon chronic-induced colitis in Muc13−/− mice and a previous study even described that MUC13 knockdown was associated with less tumor formation in AOM/DSS-treated mice." (PMID 37174625, 2023). "In response to DSS, MUC13 was protective during the acute phase whereas it caused more harm upon chronic colitis." (PMID 37174625, 2023). "In control animals, Mapk9 mRNA was upregulated in the colon due to the absence of Muc13 expression, whereas the mRNA levels of Mapk1, Mapk9, Rock2 and Snai1 were also affected upon acute colitis in Muc13−/− mice compared to their wildtype counterparts." (PMID 37174625, 2023). "mRNA expression of Cldn1 and Cldn2 was significantly altered in control Muc13−/− mice compared to wildtypes and during the course of colitis." (PMID 37174625, 2023). "MUC13, a mucin implicated in gastrointestinal homeostasis, was upregulated in the LP of mice with DSS-induced colitis treated with ES, while MUC2, a major component of mucus, was upregulated in the IEC." (PMID 28191818, 2017). "It is well established that regulating Muc2 is paramount when it comes to colitis, as Muc2 deletion leads to development of spontaneous colitis in mice, which is not seen in mice deficient in other mucins, such as Muc1 or Muc13." (PMID 38397081, 2024). "have shown that loss of Muc13 in DSS challenged mice caused severe and acute colitis." (PMID 36891301, 2023). "Moreover, opposing effects on disease activity during acute and chronic DSS-induced colitis were noticed: the presence of MUC13 was protective during the acute phase whereas it was harmful during chronic DSS administration." (PMID 37174625, 2023). "However, they also described that Muc13 deficiency in mice aggravates dextran sulfate sodium-induced colitis, attributing a protective function to Muc13." (PMID 34685068, 2021). "Although Muc1 was significantly increased during the course of colitis in DSS-treated mice, a compensatory increase in Muc1 expression was also seen upon acute colitis in Muc13−/− mice, which could explain the abolishment of the Muc13 knockdown effect on the barrier function upon DSS exposure." (PMID 37174625, 2023). "Loss of ACE2 has been associated with intestinal barrier dysfunction and aggravated colitis severity, whereas a strong correlation between ACE2 and MUC13 has been shown in airway epithelial cells and intestinal metaplastic cells of the stomach." (PMID 37174625, 2023). "In vivo intestinal permeability and MUC13-related signaling pathways affecting barrier function were investigated in acute and chronic DSS-induced colitis wildtype and Muc13−/− mice." (PMID 37174625, 2023). "Muc13−/− mice seemed to exhibit more severe clinical signs of colitis and macroscopic colonic inflammation than wildtype controls upon acute DSS colitis, whereas an enhanced recovery was noticed after the second cycle of DSS administration." (PMID 37174625, 2023). "Expression of Cldn3, Cldn4, Cldn7 and Cdh1 mRNA was however not altered during colitis or due to the absence of Muc13 expression in mice." (PMID 37174625, 2023). "Mice with DSS-induced colitis used in this study consistently showed decreased expression of ZO-1, occludin, MUC2, and MUC13, and elevated level of plasma LPS, indicating an impairment of intestinal barrier functions and thereby increased intestinal permeability." (PMID 33674694, 2021). "In addition, acute DSS treatment seemed to induce more severe clinical symptoms of colitis and higher macroscopic inflammation in the absence of MUC13, which is similar." (PMID 37174625, 2023).